OR2T7 (olfactory receptor family 2 subfamily T member 7 (gene/pseudogene))
Description:
Odorant receptor.
Synonyms: OR2T7P; OST723
Gene: Protein-coding gene on chromosome 1 (248,436,359 to 248,444,316, forward strand). Ensembl gene ENSG00000227152.
Subcellular location: Cell membrane
Pathways (Reactome):
Sensory Perception: Expression and translocation of olfactory receptors
Genetic constraint (gnomAD): Missense variants: 200 observed, 231.21 expected, observed/expected ratio (o/e) 0.87, 90% interval 0.77 to 0.97. Synonymous variants: 64 observed, 85.96 expected, observed/expected ratio (o/e) 0.74, 90% interval 0.61 to 0.92.
Homologues: Orthologues: mouse Or8g22 (27% identical), mouse Or8g29 (26% identical).